BCORP1 (BCL6 corepressor pseudogene 1)
Synonyms: FLJ39821; formerly BCORL2
Gene: Transcribed unprocessed pseudogene on chromosome Y (19,456,585 to 19,484,884, reverse strand). Ensembl gene ENSG00000215580.
Diseases named in the same sentence as BCORP1 in open-access papers:
BCORP1 is named in the same sentence as 2 diseases in open-access papers, as found by Europe PMC text mining. Sharing a sentence is not in itself a finding about the gene and the disease. The quoted sentences say what the papers report.
epilepsy (1 paper, 2025). A brain disorder characterized by episodes of abnormally increased neuronal discharge resulting in transient episodes of sensory or motor neurological dysfunction, or psychic dysfunction. "RNA-seq analysis of the iPSCs revealed that genes such as TTTY14, TBL1Y, MEG8, MEG9, BCORP1, and RPS4Y1 are not directly related to epilepsy." (PMID 40600194, 2025).
neurological diseases (1 paper, 2025). "Specifically, we chose the genes TTTY14, TBL1Y, MEG8, MEG9, BCORP1, and RPAS4Y1 for analysis, all of which were found to be unrelated to neurological diseases." (PMID 40600194, 2025).